CD163 (CD163 molecule)
Diseases named in the same sentence as CD163 in open-access papers (continued):
Sharing a sentence is not in itself a finding about the gene and the disease.
glioma (continued). "Quantification of immune cells (CD20+ B cells, CD4+ T cells, CD8+T cells, CD68+ Macrophages, and CD163+ TAMs) in our 304 glioma cases (WHO I–IV)." (PMID 32528967, 2020). "VAP-1 and TAM biomarkers (CD68, iNOS, and CD163) were evaluated by immunohistochemistry in 108 gliomas from Kaohsiung Medical University Hospital." (PMID 32349342, 2020). "In conclusion, elevated levels of VAP-1 protein in gliomas constitute a highly aggressive subgroup associated with poor outcomes, and VAP-1 co-expressed with TAM CD163 subtype is shown to be an excellent prognostic indicator for glioma patients." (PMID 32349342, 2020). "The levels of the marker for the general activated microglia, CD68, markers for M1 microglia (CD86 and MHC II) and markers for M2 microglia (CD206 and CD163) were all increased in GL261-C glioma tissue than in GL261-eGFP and GL261-vC glioma tissues." (PMID 32550897, 2020). "Increased AUC of VAP-1/CD163 coexpression further demonstrated better predictive accuracy for glioma than did VAP-1 expression alone (AUC = 0.8008)." (PMID 32349342, 2020). "Similar to our study, Liu analysis a large scale glioma data and revealed that CD163 showed a positive relationship with immune cell populations in glioma and was up-regulated in IDH wild-type glioma." (PMID 33408717, 2020). "Meanwhile, we compared the immunohistochemistry of CD163 in normal brain tissue and glioma through the human protein atlas, and found that the expression of CD163 in glioma was significantly higher than that in normal brain tissue." (PMID 32509446, 2020). "Both, CD163 and CD204, identify anti-inflammatory glioma-associated microglia/macrophages (or GAMs), which are present in higher glioma grade and consequently leading to worse survival." (PMID 31824268, 2019). "Under these conditions, it appeared that not only the number of CD163 positive cells, but also the CD163 expression level itself, were increased in high-grade gliomas as compared to low-grade ones." (PMID 31649675, 2019). "The TCGA-glioma data analysis also shows a strong expression correlation of FcγRIIB and CD163 (R = 0.82, p < 2.2e-16)." (PMID 31560714, 2019). "Taken together, these results clearly revealed a significant positive correlation between VM level and CD163+ TAM infiltration in human glioma tissues." (PMID 27903982, 2017). "The levels of VM and infiltrated CD163+cells were positively correlated with glioma grade (P < 0.01; P < 0.01, respectively)." (PMID 27903982, 2017). "Herein we reported that both VM and CD163+ cells were associated with WHO grade and reduced patient survival, and VM channel counting was correlated to the number of infiltrated CD163+ cells in glioma specimens." (PMID 27903982, 2017). "The association between VM numbers, CD163+ TAM counts and the clinicopathological status of patients with glioma was then analyzed." (PMID 27903982, 2017). "Previous studies have demonstrated that activated macrophages in glioma tissue express high levels of CD163, CD68, CD206, and CD204." (PMID 28076333, 2017). "More importantly, a correlation of CD31−PAS+ vessels and CD163+ cells was observed in glioma and normal brain tissues." (PMID 27903982, 2017). "In the present investigation we also found that CD163+ cell numbers were significantly higher in the high-grade glioma TMAs as compared to the low-grade." (PMID 28445977, 2017). "In summary, these data indicated that VM level was positively correlated with the number of infiltrated CD163+ M2-like TAMs in glioma specimens." (PMID 27903982, 2017). "CD163+ cells were present throughout the tumor tissue, and grade IV glioma specimens had the highest number of infiltrated CD163+ cells." (PMID 27903982, 2017). "In our study, to investigate how M2 macrophage played role in glioma, firstly we've analyzed the clinicopathological significance of M2 macrophage existence on clinical tissues of glioma using detection of CD163 expression with immunohistochemistry." (PMID 27765933, 2016).
glioma (continued). "Positive Immunostaining of CD163 was shown to be remarkably distributed in glioma tissues in comparison with paired normal controls." (PMID 27765933, 2016). "In glioma, the proportions of CD163+ macrophages among CD68+ macrophages, which would reflect the proportion of macrophages polarized to the M2 phenotype, were reported to be associated with histologic grade." (PMID 23555776, 2013). "Previously, glioma-derived M-CSF was shown to induces markers reflective of the M2 phenotype CD163 and CD204 on monocytes, and in turn these differentiated microglia/macrophage facilitated tumor growth." (PMID 23983766, 2013). "An immunohistochemical analysis of glioma specimens has shown that an increased number of macrophages with positive staining for CD163, which is a marker for M2 macrophages in humans, correlates with the histological grade of gliomas." (PMID 24213108, 2011). "It is worth noting that the activation and proliferation of T-lymphocytes can be impeded by soluble CD163, suggesting that soluble CD163 may also have anti-inflammatory properties and assist in the process of immune evasion of glioma cells." (PMID 40191733, 2025). "CD163 expression is increased in glioma cells, especially in primary glioma cells." (PMID 39941886, 2025). "In glioma cohorts, high CD163 likewise predicts poor prognosis." (PMID 41354084, 2025). "Multiplex fluorescent immunofluorescence of human glioma tissue further showed positive correlation of HEC1 expression in glioma with the infiltration of M2 macrophages (CD68+CD163+), the malignant degrees of gliomas, and a lower survival probability of patients with high HEC1 expression." (PMID 39021287, 2024). "Moreover, the sialic acid-dependent regulation of CD163 expression was observed both in healthy control and glioma patient-derived monocytes." (PMID 39065651, 2024). "The enhanced expression of CD86 and reduced expression of CD163 in microglia suggested that HEC1‐derived glioma cells could promote M2 polarization." (PMID 39021287, 2024). "In line with this, CD163 has been suggested as a novel therapeutic target for glioma." (PMID 39065651, 2024). "Interestingly, our data displayed that glioma induced CD163 expression on monocytes can be prevented by reducing the sialic acid content of glioma cells using a sialic acid inhibitor." (PMID 39065651, 2024). "In addition, a significant increase in CLEC7A+ CD163+ cells was observed with increasing WHO grade of glioma." (PMID 38846954, 2024). "In the GL261 glioma model, which was defined as an immunotherapy-sensitive glioma model, increased expression of M1 macrophage markers (Tnfa, Irf7, and Ifng) and decreased expression of M2 macrophage markers (Arg1, Cd206 and Cd163) were found after treatment with anti-PD1 immunotherapy." (PMID 37543576, 2023). "Finally, we conducted a study on the correlation of POLD4 expression with cell proliferation markers PCNA, tumor-associated macrophage markers (CD163, CD206), and the immune checkpoint PDL1 in glioma tissue." (PMID 37762224, 2023). "Therefore, we examined the infiltration level of immune cells (CD11b+ and CD163+) in gliomas samples by IHC staining." (PMID 35845613, 2022). "Abundant TAM (CD68+/CD163+) infiltration was observed in glioma tissues with high GSDMD expression." (PMID 35990696, 2022). "In contrast to UVM, CD163 positive cells showed only a slight inflammatory response in glioma." (PMID 35525921, 2022). "Similarly, IHC analysis revealed a strong positive correlation between TGFBI and CD163 in glioma patients." (PMID 35673564, 2022). "We also found that the M2 markers CD68 and CD163 were highly expressed in high-grade gliomas." (PMID 33898320, 2021). "Then positive correlations were shown between GSDMD and CD163 expression in glioma tissues by IHC." (PMID 34830775, 2021). "We next assessed the extent of co-expression of BTK and CD163 antibodies in a high-grade glioma." (PMID 34645618, 2021).
glioma (continued). "CD206 and CD163 protein levels were lower in the HMC3 microglia co-cultured shAEG-1 glioma cells." (PMID 34462446, 2021). "We demonstrated high expression of CD163 in glioma patients through the CPTAC proteomics database." (PMID 32509446, 2020). "CD163 expression alone is also a potential biomarker for diagnosis of glioma patients (AUC = 0.7565, Appendix Figure A2C ), whereas neither CD68 nor iNOS expression exhibits the diagnostic accuracy (CD68, AUC = 0.5851; iNOS, AUC = 0.6013) (Appendix Figure A2A,B)." (PMID 32349342, 2020). "Although VAP-1/CD68 and VAP-1/iNOS also exhibited their diagnostic properties for overall survival, they did not exhibit the same degree of diagnostic accuracy in gliomas as that of VAP-1/CD163 (VAP-1/CD68, AUC = 0.7300; VAP-1/iNOS, AUC = 0.5535)." (PMID 32349342, 2020). "LGALS3 was mainly expressed in IDH wild-type glioma and was closely related to CD163+ TAMs." (PMID 32528967, 2020). "In clinicopathological studies of malignant tumors using CD163 to detect M2-like TAMs, patients with glioma, follicular lymphoma, renal cancer, and pancreatic cancer were shown to have poorer clinical prognosis in the presence of TAMs with a higher expression of CD163." (PMID 32256354, 2020). "Due to its strong correlation with immune cell infiltration in glioma, particularly the infiltration of CD163+ TAMs, it might be a novel and promising target and could provide a novel insight into potential therapeutic strategies for immune therapy in glioma." (PMID 32528967, 2020). "Based on its prognostic significance and strong correlation with CD163+ TAMs, it may act as an important therapeutic target for human glioma." (PMID 32528967, 2020). "From double-staining, it was found that iNOS+ M1 and CD163+ M2 existed in different glioma areas." (PMID 32349342, 2020). "To investigate whether the density of M2-like TAMs correlated with the VM level in human glioma, we detected the expression of CD163 (a marker of human M2-like TAMs), CD31 and PAS (markers for vessel) in 87 human glioma specimens by immunochemical staining." (PMID 27903982, 2017). "After analysis of relevance, we found there was a closely positive correlation between VM level and CD163+ TAMs infiltration, which is a significant phenomenon and implies TAMs may involve in VM formation of glioma." (PMID 27903982, 2017). "The macrophages that were induced by both hypoxia and the hypoxia-treated glioma cell supernatants contained the highest proportions of spindle-like and CD163+ cells, imply the presence of a synergetic effect between these two hypoxic conditions on the M2 polarization of TAMs." (PMID 27602954, 2016). "Similarly, the monocyte shift toward M2/CD163+ TAMs by increased levels of M-CSF has been seen in other tumor types such as glioma, clear cell renal carcinoma, ovarian carcinoma and a mouse model of osteosarcoma." (PMID 26243145, 2015). "Furthermore, overexpression of CD163 in glioma samples correlated with poor patient prognosis." (PMID 39941886, 2025). "CD163 as a marker of M2 macrophage might contribute to predict aggressiveness and prognosis of Kazakh ESCC with the increased number of M2 macrophages, and CD163 also contributes to gliomagenesis via casein kinase 2 that might serve as a therapeutic target for glioma." (PMID 40761790, 2025). "Thus, CD163 contributes to gliomagenesis through CK2 and suggests that the CD163 pathway could serve as a therapeutic target for glioma." (PMID 39941886, 2025). "Additionally, we analyzed the correlation between POLD4 and the markers of tumor-associated macrophages, CD163 and CD206, as well as the expression of the immune checkpoint PDL1 to explore the effect of POLD4 on the immunosuppressive microenvironment in gliomas." (PMID 37762224, 2023). "Importantly, higher CD163 expression informed poorer overall survival in glioma patients." (PMID 35673564, 2022). "In addition, CD44+CD163+ cells were verified by IF on human glioma samples." (PMID 35187044, 2021).
glioma (continued). "It was reported that CD163 could act as a regulator of immune response and the potential to be a target to suppress immune escape and recover the function of T-cell populations in gliomas." (PMID 33937022, 2021). "Similarly, the relationship between SIGLEC1 and CD163 in glioma also need to be further studied." (PMID 33408717, 2020). "Increased numbers of CD68+ and higher ratio of CD163/AIF+ cells, as TAMs markers, and more FOXP3+ cells were associated with shorter progression-free survival, while high CD3+ and CD8+ T cells accompanied by low CD68+ and high IDO+ cell counts were associated with better glioma prognosis." (PMID 33050070, 2020). "Similarly, in glioma, CD163+ TAMs induce the VM by enhancing the secretion of IL-6 via PKC pathway." (PMID 32092078, 2020). "Our PathoFusion heatmaps show examples of diffuse glioma growth where strongly Iba1+ immunoreactive microglia-derived macrophages are found in spatial proximity to CD276+ GSCs, outnumbering instances where CD163 and CD276+ cells co-occur." (PMID 40136662, 2025). "Subsequently, we immunofluorescently stained tumor samples and found a co-expression pattern of CD163 and RBM47 within the glioma samples, suggesting a potential interaction between the two." (PMID 39757245, 2025). "Although EXO from glioma cells under normoxia condition also led to an increase in ARG-1 and CD163, the effect of EXO from glioma cells under hypoxic condition was more pronounced." (PMID 39407269, 2024). "To further elucidate the biological importance of HEC1, we performed multiplex fluorescent immunofluorescence staining of macrophage marker CD68, CD163, along with glioma cell marker Glial fibrillary acidic protein (GFPA), across different grade of glioma." (PMID 39021287, 2024). "Enrichment of CD8+ T cells and CD45+ leukocytes in low-grade gliomas compared to high-grade gliomas.Lowest number of infiltrating CD8+ T cells and CD163+ macrophages in diffuse midline gliomas." (PMID 38542199, 2024). "Anti-PD-L1 antibody treatment activates infiltration of CD163-positive Mφ, usually considered as an M2 Mφ marker, in a TMZ-resistant murine glioma model and also pGBM/rGBM tissue." (PMID 39409905, 2024). "Furthermore, we observed that GAMs in IDHmt gliomas exhibited a significant increase in the expression of M1‐associated markers and cytokines, such as CD86 and IL1B, and a significant decrease in M2‐associated genes, such as CD163 and CD206, relative to IDHwt counterparts." (PMID 37166058, 2023). "Results demonstrated that, when cocultured with DHX9‐overexpressed glioma cells, macrophages exhibited decreased expression of M1 markers (IL‐1b, IL‐12b, and TNF‐α) and increased expression of M2 markers (IL‐10, CD163, and ARG1)." (PMID 36377508, 2023). "As expected, the high-POLD4 group showed significantly higher expression of PCNA, CD163, CD206, and PDL1 compared to the low-POLD4 group, further confirming the correlation between POLD4 and glioma cell proliferation and the immunosuppressive microenvironment." (PMID 37762224, 2023). "The numbers of CD163- and MSR1-positive cells were higher in the GBM slices than in grade II and grade III glioma specimens." (PMID 37391426, 2023). "We collected tumor tissue samples from 20 glioma patients and performed immunohistochemical staining for POLD4, PCNA, CD163, CD206, and PDL1." (PMID 37762224, 2023). "We found that compared to the low POLD4 expression group, the high POLD4 expression group exhibited higher levels of PCNA, CD163, CD206, and PDL1 expression in glioma tissue." (PMID 37762224, 2023). "In human gliomas, TAMs are commonly identified by the expression of a broad monocyte lineage marker CD68 and M2-specific Mφ markers CD163 and CD204." (PMID 36451253, 2022). "CD163+p-STAT3+ clustering also occurred and was significantly more frequent within tumor areas of metastases than in gliomas." (PMID 35316217, 2022).
glioma (continued). "The quantity of CD8+ cells at the distance of 0–25 μm and 25–50 μm neighboring SOX10-expressed cells exploded in the Glioma WHO IV group, while the amount of CD68+CD163+ cells also increased." (PMID 36524115, 2022). "High expression of M2-like TAM markers (CD204 and CD163) in GBM predicts dismal prognostic outcome and aggressive phenotype of glioma." (PMID 36118855, 2022). "CD163+ macrophages were evident throughout the TME of metastatic tumors, whereas in gliomas, CD68+, CD11c+CD68+, and CD11c+CD68+CD163+ cell subtypes were commonly observed." (PMID 35316217, 2022). "We performed multiplex immunofluorescence in the controlled group and different grades of glioma groups to further characterize the relationship between SOX10-expressed cells and neighboring CD68+CD163+ cells, and CD8+ cells." (PMID 36524115, 2022). "By checking expression of CD44 and CD163 in glioma samples through IF, CD44+CD163+ cells were uncovered, which confirmed that the CD44+ TAMs are in M2 phenotype." (PMID 35187044, 2021). "Co-immunofluorescence (co-if) was therefore performed to further examine the extent of BTK, SOX2, and CD163 co-expression within individual cells in GBM and a low-grade glioma." (PMID 34645618, 2021). "Similar to gliomas, LMD in melanoma patients appears to demonstrate an enrichment of innate immune cells like CD68+ single cells (monocyte-derived cells) and CD163+ single cells or macrophages." (PMID 34691054, 2021). "We also observed co-expression of BTK with CD163 and CD68 in a proportion of cells from high-grade glioma tissues." (PMID 34645618, 2021). "Immunohistochemistry staining for the M2 macrophage marker CD68 and CD163, mast cell marker CD117, neutrophil marker CD66b, and RNA sequencing of glioma samples from the XYNS cohort were performed." (PMID 34489938, 2021). "The results indicated that higher expression of AEG-1 in glioma was positively correlated with the infiltration of CD206+ (r = 0.443, P = 0.001) and CD163+ (r = 0.333, P = 0.018) M2 GAMs." (PMID 34462446, 2021). "We first used immunohistochemistry from formalin-fixed paraffin-embedded (FFPE) material to assess BTK protein expression in a glioma tissue microarray (TMA) alongside immune cell markers, such as CD163." (PMID 34645618, 2021). "We demonstrated that AEG-1 knockdown in glioma cells substantially reduced the mRNA levels of M2 markers, CD206 and CD163 in co-cultured HMC3 microglia, to varying degrees in U251 and U87 co-culture systems." (PMID 34462446, 2021). "The results revealed that the expression of CD163 and FPR3 were increasing in glioma, especially in GBM, the expression of P2RY12 was high in glioma, but more notable in LGG." (PMID 33408717, 2020). "LGALS3 was closely related to IDH status, CD163+ TAMs and was mainly expressed in IDH wild-type glioma." (PMID 32528967, 2020). "We detected CD163 and CD206 by IHC staining of GL261 glioma tissue samples and found that the levels of both markers were decreased after ACT001 treatment." (PMID 32483429, 2020). "To analyze which cells co-localized with CCL2+ or CXL10+ cells in the glioma model, we used the stem cell marker Nestin, a microglia marker Iba-1, and the M1- and M2-type monocyte macrophage markers CD16 and CD163, respectively." (PMID 32943658, 2020). "Hence, CD163 might serve as a therapeutic target for glioma." (PMID 33408717, 2020). "In a total of 108 glioma patients, VAP-1 expression and VAP-1/CD163 coexpression were both correlated with age, grade, survival, and IDH1 mutations." (PMID 32349342, 2020). "High percentages of glioma patients with positive VAP-1/CD68 (65.75%) and VAP-1/CD163 (73.13%) co-immunoreactivity were apparently observed." (PMID 32349342, 2020). "Several molecules have been reported as specific markers of TAMs in glioma, including CD204, CD163, CD11b, CD14, and CD68." (PMID 31140757, 2019).